ZNF738 (zinc finger protein 738)
Description:
May be involved in transcriptional regulation.
Tractability: PROTAC: ubiquitination databases record sites on it.
Gene: Protein-coding gene on chromosome 19 (21,358,930 to 21,388,582, forward strand). Ensembl gene ENSG00000172687.
Subcellular location: Nucleus
Pathways (Reactome):
Gene expression (Transcription): Generic Transcription Pathway
Gene Ontology:
Molecular function: DNA-binding transcription factor activity; RNA polymerase II cis-regulatory region sequence-specific DNA binding; ubiquitin-protein transferase activity
Biological process: protein polyubiquitination; regulation of DNA-templated transcription
Cellular component: nucleus
Homologues: Orthologues: mouse Zfp738 (42% identical), mouse Zfp457 (41% identical), mouse Zfp595 (41% identical), rat AABR07009105.1 (39% identical), mouse Zfp953 (33% identical). Paralogues in human: ZNF493 (71% identical), ZNF254 (66% identical), ZNF708 (66% identical), ZNF681 (65% identical), ZNF724 (64% identical), ZNF429 (64% identical), ZNF726 (63% identical), ZNF728 (63% identical), ZNF85 (62% identical), ZNF93 (60% identical), ZNF43 (60% identical), ZNF714 (59% identical), and 164 more.
Diseases named in the same sentence as ZNF738 in open-access papers:
ZNF738 is named in the same sentence as 2 diseases in open-access papers, as found by Europe PMC text mining. Sharing a sentence is not in itself a finding about the gene and the disease. The quoted sentences say what the papers report.
cancer (2 papers, 2017 to 2022). A tumor composed of atypical neoplastic, often pleomorphic cells that invade other tissues. "No previous research studies were published concerning the relationship between cancer and HGSNAT or ZNF738." (PMID 35910199, 2022). "Other MS loci display marked cancer-type specificity, for example, MSI events within the 5′ UTR region of ZNF738, C10orf140, ZNF271 and RAB28 are specific to COAD tumours, whereas those in EBP, TMEM182, MIR567 and MEIS1 are absent or substantially depleted in STAD compared to COAD and UCEC tumours." (PMID 28585546, 2017).
ZNF738 also shares sentences with these, for which no sentence is quoted: tumours (1 paper).